SNORD91B (small nucleolar RNA, C/D box 91B)
Synonyms: HBII-296b
Gene: Small nucleolar RNA gene on chromosome 17 (2,329,016 to 2,329,237, reverse strand). Ensembl gene ENSG00000275084.
Gene Ontology:
Biological process: RNA processing
Cellular component: nucleolus